IGSF11 (immunoglobulin superfamily member 11)
Diseases named in the same sentence as IGSF11 in open-access papers (continued):
Sharing a sentence is not in itself a finding about the gene and the disease.
tumor (25 papers, 2017 to 2025). "On the diagnostic front, the restricted expression pattern of IGSF11 in normal tissues is mainly limited to the testis and brain, enhancing its specificity as a tumor-associated antigen." (PMID 40867265, 2025). "Overall, the UALCAN graph underscores the tumor-specific upregulation of both IGSF11 and VISTA across a range of cancer types compared to normal counterparts, reinforcing their relevance as potential targets in immune checkpoint blockade strategies." (PMID 40867265, 2025). "iOmx Therapeutics has developed next-generation cancer immunotherapies with a focus on IMT-18, an antibody targeting IGSF11 to overcome tumor-induced immune suppression, particularly in PD-1/PD-L1-resistant tumors." (PMID 40867265, 2025). "IGSF11 is widely expressed across multiple tumor types, though its regulatory mechanisms vary depending on the malignancy." (PMID 40506491, 2025). "IGSF11 is increasingly recognized for its immunosuppressive function as well as its potential role in promoting tumor progression and metastasis." (PMID 40867265, 2025). "Integrated anti-IGSF11 therapy in conjunction with conventional anti-tumor therapy modalities has potential in reversing suppression of the immune system and enhancing therapeutic efficacy." (PMID 40867265, 2025). "Although direct mechanistic studies on IGSF11’s role in metastasis are limited, its dual involvement in tumor immune evasion and microenvironment remodeling strongly suggests that it contributes to both local tumor progression and distant metastasis." (PMID 40867265, 2025). "Functional studies have demonstrated that genetic silencing or inhibition of IGSF11 enhances anti-tumor immunity." (PMID 40867265, 2025). "As a ligand for the immune checkpoint receptor VISTA, IGSF11 plays a central role in suppressing T-cell activation and facilitating immune evasion in the tumor microenvironment." (PMID 40867265, 2025). "Collectively, these studies highlight the emerging role of IGSF11 as a critical immunoregulatory molecule within the tumor microenvironment, primarily through its interaction with VISTA and its capacity to modulate cytokine signaling pathways." (PMID 40867265, 2025). "Xiyang Tang’s research shows that IGSF11 and Vista are a pair of immune checkpoints, which act on tumor proliferation and immune regulation, and have great potential as new tumor immunotherapy targets and biomarkers." (PMID 36482887, 2022). "IGSF11 proved to be highly accumulated in tumor cells and VISTA raised more in both immune cells and malignant cells; the expression of these are modulated by signal pathways and epigenetic regulation." (PMID 35831836, 2022). "These include alterations in e.g. MSH4, PRDM2, and TP53I3 in the MSI tumor as well as GATA, DOCK5, and IGSF11 in the MSS tumor." (PMID 28683819, 2017). "Given its dual role in immune regulation and tumor progression, IGSF11 holds promise as a predictive biomarker for checkpoint inhibitor responsiveness, as well as a prognostic marker for cancer aggressiveness, and potentially also for immune landscape characterization." (PMID 40867265, 2025). "Importantly, targeting IGSF11 enhances prostimulatory cytokine production, promotes T-cell recruitment, and reinvigorates anti-tumor immune responses, effectively converting immunologically “cold” tumors into “hot” ones." (PMID 40867265, 2025). "This provides a significant opportunity for further research into IGSF11’s role in tumor immune regulation, especially since its intracellular mechanisms remain largely unknown." (PMID 40867265, 2025). "This overexpression suggests a potential role of IGSF11 in tumor progression and immune modulation." (PMID 40867265, 2025). "Beyond immune modulation, emerging evidence suggests that IGSF11 may directly influence tumor cell behavior." (PMID 40867265, 2025).
tumor (continued). "Targeting IGSF11 may therefore represent a strategic approach to suppress tumor growth and prevent metastatic spread by restoring immune control and disrupting pro-tumorigenic signaling networks." (PMID 40867265, 2025). "By inhibiting IGSF11 function, K284-3046 may enhance T-cell activity and potentially improve anti-tumor immune responses." (PMID 40867265, 2025). "Therapeutically, targeting the IGSF11 axis may provide a novel means to reverse immune suppression, enhance T-cell-mediated anti-tumor responses, and potentially overcome resistance to existing checkpoint blockade therapies." (PMID 40867265, 2025). "According to our review and bibliometric study, VISTA and its ligands, especially for IGSF11, may be the novel and promising target in tumor immunotherapy." (PMID 35831836, 2022). "This may prove to be a breakthrough to solve the current clinical immune resistance, and most importantly, since research has focused on VISTA but less on IGSF11, IGSF11 may be the next candidate for tumor immunotherapy." (PMID 35831836, 2022). "Together, these observations suggest that tumor cells may use IgSF11 in addition to other previously reported immune checkpoints, such as PD-1 and PDL-1 axis, to institute an immune suppressed microenvironment." (PMID 33604291, 2020). "Moreover, IGSF11 expression was positively correlated with the expression of several critical immune checkpoint molecules, suggesting its involvement in modulating immune responses within the tumor microenvironment." (PMID 40867265, 2025). "Furthermore, combinatorial strategies targeting IGSF11 along witother checkpoints may enhance anti-tumor immunity and overcome resistance to existing immunotherapies." (PMID 40867265, 2025). "Furthermore, liquid biopsy approaches to detect IGSF11 mRNA or circulating tumor-derived exosomes carrying IGSF11 may offer minimally invasive diagnostic tools for early detection or monitoring of treatment response." (PMID 40867265, 2025). "IGSF11 serves as a key modulator of cellular interactions within the TME, orchestrating complex signaling between tumor cells, immune infiltrates, and stromal components." (PMID 40867265, 2025). "Blocking IGSF11 disrupts its interaction with VISTA, releasing T-cell inhibition and restoring effector functions in the tumor microenvironment." (PMID 40867265, 2025). "The UALCAN pan-cancer analysis graph illustrates the differential mRNA expression levels of IGSF11 and VISTA (C10orf54) across various tumor types in comparison to their corresponding normal tissues using the TCGA database." (PMID 40867265, 2025). "As a binding partner of VISTA, IGSF11 contributes to T-cell suppression within the TME, thereby facilitating tumor immune escape." (PMID 40867265, 2025). "Monoclonal antibodies such as IMT-18 disrupt the IGSF11–VISTA interaction, restoring T-cell function within the tumor microenvironment." (PMID 40867265, 2025). "Preclinical and clinical trials all emphasize the predictive role of IGSF11 and VISTA in the prognosis of tumors, and that the predictive role of the same gene varies from tumor to tumor." (PMID 35831836, 2022). "Taken together, IGSF11 and VISTA are both highly accumulated in tumors, and participate in the regulation of tumor growth, immune microenvironment, therapy resistance and prognosis prediction." (PMID 35831836, 2022). "IGSF11 and VISTA are also a pair of immune checkpoints that exert in tumor proliferation and immune regulation, which has enormous potential to be used as a novel tumor immunotherapy target and biomarker." (PMID 35831836, 2022). "Besides, more research focuses on the expression regulation signal pathways and epigenetic regulation of VISTA but less on IGSF11, and studying the corresponding IGSF11 expression regulation mechanism may provide more targets for IGSF11 downregulation and contribute further to tumor immunotherapy." (PMID 35831836, 2022).
tumor (continued). "At present, further research is proving the enormous potential of IGSF11 and VISTA in tumors, and especially the role of VISTA in tumor immune resistance." (PMID 35831836, 2022). "The interaction between IGSF11 and VISTA can be affected by the pH of TME (tumor microenvironment), the binding affinity between IGSF11 and VISTA at pH 7.4 is 20 nM, but 80 nM at pH 6.0 (often seen in TME)." (PMID 35831836, 2022). "Decreased miR-125a-5p, known to influence immune-checkpoint signaling via IGSF11/VSIG3, may reflect reduced baseline anti-tumor immune tone." (PMID 41441242, 2025). "A combination of IGSF11 inhibition with anti-PD-1 or anti-CTLA-4 treatments can augment the activation of T-cell populations, activate the exhausted T-cell pools, and enhance the repertoire of immunity toward the tumor antigens." (PMID 40867265, 2025). "Adjacent to VISTA’s regulatory mechanisms, VSIG-3, or IGSF11, serves as a ligand for VISTA, implicated in cell adhesion processes and expressed predominantly in human tumor cell lines, testes, and ovaries, with lesser expression noted in the brain and kidneys." (PMID 40777027, 2025). "Monoclonal antibodies designed to block IGSF11 may disrupt its interaction with VISTA, and restore T-cell activity within the tumor microenvironment." (PMID 40867265, 2025). "Given that VISTA is also accumulated in cytoplasm of tumor cells, we consider that VISTA may bind with IGSF11 in cytoplasm and exert in tumor proliferation, but this hypothesis warrants more confirmation." (PMID 35831836, 2022). "Various studies have proved that VISTA coordinates with PD1/PD-L1 in tumor immune regulation but not for IGSF11." (PMID 35831836, 2022). "Beyond Sema4F, multiple axon-related molecules, classified for their function in tumor axonogenesis, such as Bmp7, Robo1, Fibronectin, or Nrp1, and the synaptic adhesion molecule IGSF11/VSIG-3 are regulated upon TGFβ−mediated EMT induction, hnRNP E1 silencing, or Platr18 overexpression." (PMID 34810279, 2022). "Both IGSF11 and VISTA have the potential to be the novel target in tumor immunotherapy." (PMID 35831836, 2022). "Both IGSF11 and VISTA have the potential to be the novel targets in tumor immunotherapy." (PMID 35831836, 2022). "The downregulation of either IGSF11 or VISTA in various tumor models, significantly inhibits tumor growth, and the mechanisms of VISTA may be attributed to the restoration of T cells, but the mechanisms of IGSF11 are still unknown." (PMID 35831836, 2022).
cancer (17 papers, 2020 to 2025). A tumor composed of atypical neoplastic, often pleomorphic cells that invade other tissues. "While IGSF11 is closely associated with patient prognosis, its prognostic significance differs among cancer types." (PMID 40506491, 2025). "Despite these challenges, IGSF11 offers a compelling opportunity as a novel immune checkpoint molecule, particularly in cancers where VISTA-mediated immune evasion is prominent." (PMID 40867265, 2025). "This includes the downregulation of key cytokines such as interleukin-17 (IL-17), chemokine ligand 3 (CCL3), C-X-C motif chemokine 11 (CXCL11), and chemokine ligand 5 (CCL5), providing a theoretical basis for targeting IGSF11 in cancer immunotherapy." (PMID 40867265, 2025). "To date, the immune regulatory role of IGSF11 has been demonstrated in a small number of cancer types, whereas VISTA’s involvement has been validated in a broader range of tumors." (PMID 40867265, 2025). "Nonetheless, translating these findings into clinical practice remains a significant challenge, underscoring the need for continued research into the molecular mechanisms and therapeutic potential of IGSF11 in cancer immunotherapy." (PMID 40867265, 2025). "IGSF11 has emerged as a critical immune regulatory molecule with significant implications in cancer biology." (PMID 40867265, 2025). "The following sections explore the role of IGSF11 in specific cancer types in detail, and highlight its biological significance and clinical implications." (PMID 40867265, 2025). "Targeting IGSF11 with IMT-18 represents a promising strategy to enhance the efficacy of cancer immunotherapy." (PMID 40867265, 2025). "In these studies that are compatible with the present investigation, it has also been demonstrated that IgSF11 expression is upregulated in these types of cancer." (PMID 33604291, 2020). "In this review, we focus on the immunomodulatory functions of IGSF11, its role in combination immunotherapies, and preclinical evidence supporting its potential as a novel therapeutic target to overcome resistance and improve cancer immunotherapy outcomes." (PMID 40867265, 2025). "Moreover, combining IGSF11 inhibition with established therapies such as anti-PD-1/PD-L1 improves treatment efficacy in various cancer models." (PMID 40867265, 2025). "Additionally, given that high IGSF11 expression is crucial for cancer cell growth, small-molecule inhibitors that block IGSF11 or its downstream signaling pathways may also serve as promising therapeutic options." (PMID 40867265, 2025). "Through the IGSF11/VISTA axis, it suppresses T cell function and represents a promising novel target for cancer immunotherapy." (PMID 40506491, 2025). "When used in combination with existing therapies such as anti-PD-1/PD-L1, IGSF11-VISTA axis inhibition enhances treatment outcomes by boosting inflammation and immune cell infiltration, making it a powerful immune modulator in emerging cancer therapies." (PMID 40867265, 2025). "Immunohistochemical (IHC) detection of IGSF11 protein levels in biopsy samples may aid in stratifying patients based on immune checkpoint activity, particularly in VISTA-dominant cancers where PD-1 expression is low." (PMID 40867265, 2025).
IGSF11 also shares sentences with these, for which no sentence is quoted: gastrointestinal tumors (4 papers); breast tumor (3); colorectal cancer (3); psychiatric disorder (2); schizophrenia (2); Anorexia (1); Anxiety (1); asthma (1); attention deficit-hyperactivity disorder (1); autoimmune disease (1); Azoospermia (1); bipolar disorder (1); bladder cancer (1); colon adenocarcinoma (1); colorectal adenocarcinoma (1); esophageal carcinoma (1); Infertility (1); intestinal cancer (1); invasive ductal breast carcinoma (1); liver cancer (1); myeloid leukemia (1); myxoma (1); non-small cell lung carcinoma (1); oligoastrocytoma (1); oligodendroglioma (1); osteoarthritis (1); ovarian carcinoma (1); prostate carcinoma (1); rectal adenocarcinoma (1); skin cutaneous melanoma (1).